CRP (C-reactive protein)
Diseases named in the same sentence as CRP in open-access papers (continued):
Sharing a sentence is not in itself a finding about the gene and the disease.
acute kidney injury (continued). "Moreover, we and others have demonstrated that CRP velocity between two serial measurements within the first days of hospitalization is associated with increased mortality, left ventricular dysfunction, microvascular damage, and acute kidney injury." (PMID 35566579, 2022). "For example, CRP levels are often monitored in patients with acute kidney injury (AKI) wherein they correlate with increased AKI risk, severity, and clinical outcomes." (PMID 31620123, 2019). "Elevated CRP levels contribute to acute kidney injury by impairing the regeneration of tubular epithelial cells through the inhibition of the CDK2/cyclin E pathway mediated by Smad3." (PMID 40243457, 2025). "Initial assessment revealed very high C-reactive protein (CRP), severe hyperglycemia, and acute kidney injury (AKI Stage 3)." (PMID 41631218, 2025). "For example, to acute kidney failure, the 3 inflammatory factors CRP, eosinophils, and leukocytes respectively contributed 10.5%, 8.2%, and 1.9% of the effect." (PMID 40464054, 2025). "Initial blood tests revealed a C-reactive protein (CRP) of 390 mg/L and acute kidney injury with a glomerular filtration rate (GFR) of 7 mL/min/1.73 m2." (PMID 41531583, 2025). "Laboratory tests showed leucocytosis (elevated white cell count of 32.1 × 109/L with high neutrophils of 30.5 × 109/L), elevated C-reactive protein (CRP) of 207 mg/L, and stage 1 acute kidney injury (AKI)." (PMID 41186785, 2025). "Significant factors predicting recurrent SBP included acute kidney injury, elevated CRP levels, low serum albumin levels, high serum bilirubin levels, reduced β-blocker use, increased proton-pump inhibitor use, and a higher MELD Score (odds ratio > 1 for all)." (PMID 41353185, 2025). "Elevated C-reactive protein (CRP) and myoglobinuria were also observed, and some patients were diagnosed with renal failure." (PMID 40249406, 2025). "Laboratory tests showed leukocytosis with marked eosinophilia, thrombocytosis, elevated C-reactive protein, and acute kidney injury; liver enzymes and amylase/lipase were normal." (PMID 41356895, 2025). "On admission, laboratory results revealed acute kidney injury, with a serum creatinine of 5.8 mg/dL (compared with 1.7 mg/dL measured 10 days earlier), and a C-reactive protein (CRP) level of 121 mg/L (normal range <5 mg/L)." (PMID 41438740, 2025). "NEUT-RI, PCT, and CRP values were significantly different in the patients with “renal failure” than those with “normal renal function” in the overall population." (PMID 38667467, 2024). "Initial laboratory examinations revealed slightly high serum levels of C-reactive protein (CRP: 0.91 mg/dL) and indicated dehydration and renal failure (blood urea nitrogen: 56.6 mg/dL, creatinine: 1.54 mg/dL)." (PMID 39463789, 2024). "Elevated biomarkers, such as urea, creatinine, CRP, and D-dimer, were more common in patients with renal failure, indicating a severe inflammatory response and renal impairment." (PMID 39006555, 2024). "As the diagnostic process evolved, the patient’s inflammatory labs (ESR, CRP) coupled with worsening acute kidney injury and hematuria allowed the discussant to expand the differential to vasculitis syndromes." (PMID 38512508, 2024). "In case of CAP, biological findings suggestive of LD are hyponatremia, hepatic cytolysis, renal failure and high level of C-reactive protein (CRP)." (PMID 38530466, 2024). "Patients with renal failure had elevated levels of urea, creatinine, C-reactive protein (CRP), D-dimer, white blood cell (WBC), neutrophil (Neu), and procalcitonin (PCT) (p<0.001 for all)." (PMID 39006555, 2024). "Laboratory findings indicated significant inflammation, evidenced by elevated CRP and d-dimer levels, alongside signs of acute kidney injury and metabolic disturbance." (PMID 39697904, 2024).
acute kidney injury (continued). "PCT dosage is superior to c-reactive protein and Interleukin 6 in predicting acute renal failure (7 n-RCTs, moderate certainty) and severe acute biliary pancreatitis (18 n-RCTs, low certainty)." (PMID 37450700, 2024). "Laboratory diagnostics revealed elevated lactic acid, leukocytosis, acute kidney injury, undetectable thyroid stimulating hormone, and elevations in T3, T4, C-reactive protein, brain natriuretic peptide, and creatinine kinase." (PMID 39221377, 2024). "Urinary analysis displayed glomerular hematuria and laboratory testing showed acute kidney injury with pronounced elevation of CRP and ANCA-level." (PMID 39300109, 2024). "Patients with renal failure showed significantly elevated levels of urea, creatinine, CRP, D-dimer, white blood cell (WBC), neutrophil (Neu), and procalcitonin (PCT) (p<0.001 for all)." (PMID 39006555, 2024). "Prognostic factors associated with mortality included advanced age, higher C-reactive protein (CRP) value, acute kidney failure, and acute respiratory failure." (PMID 38436032, 2024). "Significantly higher values of PCT, IL-6, and CRP (p < 0.05 for all) were observed in patients who were diagnosed with acute kidney injury (AKI) on admission and in patients who later started continuous renal replacement therapy (CRRT)." (PMID 39457628, 2024). "Hematological investigations confirmed an elevated C-reactive protein (CRP) at 281 mg/L and acute kidney injury." (PMID 39151535, 2024). "Independent predictors for troponin enhancement were acute coronary syndrome presentation, renal failure, elevated C-Reactive protein and multiple lesions treated with RA." (PMID 36835980, 2023). "In a previous review article, the predictors of severe COVID‐19 were preexisting renal failure, oxygen requirement during admission, acute kidney injury, and CRP at the time of admission." (PMID 37779668, 2023). "Using multiple linear regression analysis, ACS presentation, renal failure, elevated C-Reactive protein and the presence of multiple lesions treated with RA during the index procedure were independently associated with HS-TnT release." (PMID 36835980, 2023). "In univariate analysis, older age, male gender, the Charlson comorbidity index > 1, renal failure, increased C-reactive protein, SpO2/FiO2 ratio < 3.70 and increased respiratory rate were all associated with in-hospital mortality." (PMID 37045983, 2023). "Elevated CRP, renal failure (elevated creatinine and/or creatinine clearance) and elevated alkaline phosphatase have been associated with worse mortality among patients with MM." (PMID 35365604, 2022). "The results suggested that CRP levels above the median (108 mg/L) were correlated with venous thromboembolism, acute kidney injury, critical illness, and mortality, in comparison with CRP levels below the median." (PMID 36267156, 2022). "Comparatively, higher levels of C-reactive protein, lactate, red blood cell distribution width, and Simplified Acute Physiology Score 3 were found in the acute kidney injury group." (PMID 35544897, 2022). "The main clinical predictors were age, CRP value at admission, invasive mechanical ventilation, occurrence of infection or acute kidney injury." (PMID 35729416, 2022). "Chisan® also reduced the blood level of pro-inflammatory markers IL-6, C-reactive protein, and creatinine, suggesting prevention of renal failure progression in long COVID." (PMID 36015163, 2022). "Multivariate logistic analysis showed that an age older than 60 years, CRP value > 75 mg/l at admission, invasive mechanical ventilation, occurrence of infection or acute kidney injury were independent predictors of mortality in patients with severe COVID-19." (PMID 35729416, 2022). "In a logistic regression, predictors of 1 year mortality were the Charlson score, CRP levels, acute renal failure, and infection with E. coli resistant to 3rd generation cephalosporins." (PMID 35751036, 2022).
acute kidney injury (continued). "Laboratory parameter values showed increased white blood cell (WBC) count and C-reactive protein (CRP), substantial acute kidney injury, and severe deterioration of liver biochemistry compared to a recent previous evaluation." (PMID 33992114, 2021). "Substantial amendment (version 1.2) of addition of urinary NGAL assays, with paired serum NGAL & CRP assays, to increase sensitivity of acute kidney injury has also been approved." (PMID 33552490, 2021). "For instance, during acute kidney injury in mice, CRP promotes MDSC generation, expansion, and renal infiltration, thereby driving the injury response." (PMID 33154749, 2020). "Further reports have shown other predictors of poor outcome such as acute kidney injury, acute hepatic injury, the need for mechanical ventilation, elevated c-reactive protein (CRP), interleukin-6 (IL-6), lymphocyte count, and Procalcitonin levels." (PMID 33028914, 2020). "Blood test results revealed leucopenia, lactic acidosis, acute renal failure and high C-Reactive Protein (CRP)." (PMID 31243609, 2019). "Twelve of the 13 (92%) patients had raised CRP, and 6/13 (46%) had acute kidney injury (AKI) at presentation." (PMID 31431986, 2019). "In an unconditional logistic regression analysis, renal failure, CRP, PCT, albumin, leucocytes, and the PCT/albumin ratio at admission were significantly associated with urosepsis." (PMID 29995751, 2018). "Remarkably, organ dysfunction, such as acute kidney injury and severe hepatitis, was found in a majority of patients who had extremely high CRP levels." (PMID 26247033, 2015). "Serum resistin concentrations were closely correlated to inflammatory parameters such as C-reactive protein, leukocytes, procalcitonin, and cytokines such as IL6 and TNF-α, as well as associated with renal failure and liver synthesis capacity." (PMID 19545363, 2009). "Serum biochemistry revealed acute kidney injury, positive D-dimmer's and increased C reactive protein." (PMID 20062673, 2009). "Serum biochemistry revealed raised urea (15.1 mmol/L) and creatinine (114 umol/L) levels consistent with acute kidney injury, positive D-dimmer's levels and increased CRP (48.2 mg/L)." (PMID 20062673, 2009). "Data providing contribution of serum CRP to valve calcification in the clinical setting is available in patients with renal failure." (PMID 16774687, 2006). "Any postoperative alteration could lead to an increase in CRP, as seen with cardiovascular problems and acute kidney failure." (PMID 40392334, 2025). "Patients with CRP above the median are more susceptible to VTE and acute kidney injury." (PMID 40364223, 2025). "Although it is established that aggressive fluid replacement is associated with many adverse effects like acute renal failure and ARDS, and it might also be associated with higher CRP levels and hence, worse outcomes." (PMID 39678630, 2024). "NEUT-RI, PCT, and CRP values were significantly different in patients with “renal failure”." (PMID 38667467, 2024). "However, the independent contribution of more commonly available biomarkers of inflammation, such as WBC or CRP levels, has rarely been confirmed, or only in specific subgroups of patients, such as those with renal failure." (PMID 38681861, 2024). "It should be noted that monitoring the CRP level during treatment may be of benefit, as elevated levels heralded the development of renal failure in some cases." (PMID 39330907, 2024). "Similarly, CRP concentration was significantly elevated in anemic neonates with acute kidney injury." (PMID 37763711, 2023). "Elevated CRP levels represent a prognostically unfavourable situation, as it has been proven to be predictable for increased rates of adverse cardiac events, poor in-hospital outcomes, acute kidney injury, and mortality." (PMID 35893287, 2022).
acute kidney injury (continued). "In patient B, accounting for the near normal CRP level in the setting of necrotizing fasciitis (status post debridement less than 24 ​h before her first dose of 700 ​mg of leronlimab), acute renal failure and acute hypoxemic respiratory failure cannot account for this value." (PMID 33521616, 2021). "Furthermore, KIM-1 (an early biomarker of acute kidney injury) and CRP (a biomarker of inflammation) were significantly reduced in the AG, PAL and PAH groups." (PMID 34281284, 2021). "Inflammation may affect Apo A1 metabolism to some extent in patients with renal failure, and CRP was found to be significantly higher in the CVD group than in the non-CVD group." (PMID 33913384, 2021). "Moreover, effects on in vivo oxidative and inflammatory markers (e.g., glutathione peroxidase, superoxide dismutase, catalase, and C-reactive protein) should also be evaluated in animal models, as oxidative stress is mainly responsible for renal failure." (PMID 30991760, 2019). "C-reactive protein (CRP), was recently reported to be closely associated with poor renal function in patients with acute kidney injury (AKI), but whether CRP is pathogenic or a mere biomarker in AKI remains largely unclear." (PMID 28886014, 2017). "Levels of serum C-reactive protein did correlate with the presence and severity of coronary, cerebral, and peripheral atherosclerosis in the person with preserved renal function and in patients with different stages of renal failure and dialysis." (PMID 25648331, 2015). "Moreover, a high C-reactive protein (CRP) level on admission correlated with renal failure in the course of the disease (p = 0.003)." (PMID 22292070, 2012). "Laboratory tests revealed an increase in C‐reactive protein (CRP) (13.61, normal values < 0.5) and acute kidney injury (AKI) (creatinine 2.6 mg/dL and urea 54 mg/dL)." (PMID 41477245, 2025). "Laboratory tests revealed severe renal failure (according to the RIFLE (risk, injury, failure, loss, and end-stage kidney disease) criteria, this corresponds to stage F - failure), without electrolyte disturbances, and with elevated C-reactive protein (CRP) levels." (PMID 40851687, 2025). "Blood tests on admission showed marked myelosuppression, elevated CRP, acute kidney injury (AKI) (KDIGO stage 1), and elevated creatine kinase (CK) and transaminases." (PMID 40046360, 2025). "Laboratory results showed significant abnormalities with further elevation of her WCC at 26.3 x 109/L, CRP at 155 mg/dL, new acute kidney injury (AKI) of stage 1, and an elevated lactate at 4.8 mmol/L." (PMID 40296921, 2025). "ED: emergency department; RLQ: right lower quadrant; RIF: right iliac fossa; CRP: C-reactive protein; AKI: acute kidney injury; LFTs: liver function tests; IV: intravenous; CT: computed tomography; US: ultrasound; H." (PMID 41356895, 2025). "Therefore, in the presence of leucocytosis, neutrophilia, increased CRP, leukocyturia, and increased creatinine levels, the diagnoses of pyelonephritis and acute renal failure were assumed, and the patient was admitted to the home hospital department and started treatment with ceftriaxone." (PMID 38910633, 2024). "Other abnormal laboratory investigations recorded in multiple patients included deranged liver function tests (LFTs) in 5 (26.3%), acute kidney injury (AKI) in 3 (15.8%) and raised C-reactive protein (CRP) in 2 (10.5%)." (PMID 39696215, 2024). "The selenium intervention significantly raised the incidence of Acute Kidney injury (RR 0.76; 95% CI: 0.59, 0.98; P = 0.04) while significantly reducing the duration of hospital stay (MD -1.33; 95% CI: -2.51, -0.16; P = 0.03) and postoperative CRP levels (SMD -0.18; 95% CI: -0.34, -0.02; P = 0.03)." (PMID 38659018, 2024). "In preterm neonates with acute kidney injury (AKI), elevated CRP emerged as a critical factor influencing AKI." (PMID 38281018, 2024).
acute kidney injury (continued). "Finally, for the third experiment, higher values on cardiac dysrhythmia, glucose, cardiogenic Shock, LDH, acute kidney failure, Urea, C-reactive protein, Nr of Segments with Injury 2, RDW-CV and prothrombin time were found to be associated with a higher predicted probability of mortality." (PMID 37072766, 2023). "For example, in mice subjected to surgery-induced bilateral renal ischemia/reperfusion (I/R) injury, a procedure that faithfully mimics acute kidney injury (AKI) in humans receiving kidney transplants, we showed that CRP contributes to the pathogenesis of AKI." (PMID 33633738, 2020). "Initial laboratory investigations revealed a mildly elevated C-reactive protein (CRP), with evidence of mild acute kidney injury." (PMID 41322790, 2025). "Her C-reactive protein (CRP) was found to be raised at 218 mg/L, and she had an acute kidney injury with a creatine of 114 micromol/L." (PMID 40070887, 2025). "Laboratory investigations showed a lactate level of 3 mmol/L, a white blood cell count of 16 × 109/L, a C-reactive protein (CRP) level of 65 mg/L, and serum creatinine indicating stage 1 acute kidney injury (AKI)." (PMID 40125223, 2025). "Blood investigations showed raised septic parameters such as C-reactive protein (CRP) and white blood cell count (WBC) with mild acute kidney injury." (PMID 40351976, 2025). "Laboratory tests on admission revealed raised white cell and neutrophil count, high C-reactive protein (CRP), and significant acute kidney injury." (PMID 40772196, 2025). "Laboratory findings demonstrated metabolic acidosis, hyperglycemia, ketonemia, elevated troponin, B-type natriuretic peptide (BNP), C-reactive protein (CRP), deranged liver function, and acute kidney injury." (PMID 41426882, 2025). "These factors comprise age, septic shock, acute kidney injury, metabolic acidosis, neoplasm, BUN, CRP, and albumin." (PMID 39103964, 2024). "Blood tests done indicated markedly elevated C-reactive protein (CRP) at 500 mg/L (ref: < 10 mg/L), procalcitonin was 90 ng/ml (ref: 0.1 - 0.5 ng/ml) and was in Stage 2 acute kidney injury." (PMID 39286694, 2024). "In this study, the LPS group has experienced acute kidney injury, as evidenced by elevated BUN and Cr levels with high CRP levels." (PMID 39459616, 2024). "Compared to class B, class A was characterized by a younger age, higher CRP and PCT levels, and a higher incidence of coagulation dysfunction, liver failure, circulatory failure, and renal failure." (PMID 39844833, 2024). "Blood tests revealed elevated aspartate transaminase, alanine transaminase, C-reactive protein (CRP), and bilirubin; acute kidney injury; increased white blood cells; and abnormal coagulation parameters." (PMID 39411641, 2024). "Subsequently, he presented with multiple purpuras on his extremities, joint swelling on his fingers, abdominal pain, and diarrhea, accompanied by acute kidney injury (AKI), increased proteinuria, hematuria, and elevated C-reactive protein levels." (PMID 39206190, 2024). "PLWH who died were older than 50 years old, females, smokers, had acute kidney injury, CD4 less than 200 mm3, hypoxemic, high CRP, and HbA1c." (PMID 36855103, 2023). "Blood tests showed hepatitis with cytolysis and cholestasis (7–10 times the ULN values, respectively), acute kidney injury (KDIGO stage 1), and hyperinflammation (ferritin 2,000 μg/L and C-reactive protein 107 mg/L)." (PMID 36225555, 2022). "Investigations revealed a CRP of 261mg/L, total WCC of 14.4 × 109/L with a neutrophilia (13.4 × 109/L), acute kidney injury with serum creatinine 113μmol/L (CrCl 55mL/min)." (PMID 33743624, 2021). "At 7 days, acute kidney injury on admission, elevated LDH, tachypnea, and hyperglycemia were the strongest drivers of critical event prediction, while higher age, anion gap, and C-reactive protein were the strongest drivers of mortality prediction." (PMID 33027032, 2020).